TNF (tumor necrosis factor)
Diseases named in the same sentence as TNF in open-access papers (continued):
Sharing a sentence is not in itself a finding about the gene and the disease.
tuberculosis (continued). "Although there has been no consensus on the risk of infections associated with anti-TNFα treatments in published clinical trials, post-marketing surveillance has shown an increase in the risk of tuberculosis and other granulomatous infections." (PMID 34790122, 2021). "Remarkably, we also observed that most patients carrying the GG genotype showed a superior response to TNFi, but there were still some patients suffering from AE, such as somatic pains, iritis, or tuberculosis, which led them to switch to another TNFi or even abandon anti-TNF-α treatment." (PMID 35126146, 2021). "It has been hypothesized that HDTs that modulate TNF-α as an adjunct to canonical chemotherapy shorten therapy duration, reduce pathology, and limit tuberculosis relapse in experimental models by decreasing exacerbated inflammation." (PMID 33510265, 2021). "In this study, the prevalence of ATB in RA patients was similar to that in the general population, which may be related to the prophylaxis of tuberculosis in patients initiating anti-TNF treatment." (PMID 34753408, 2021). "Therefore, prior to the administration of TNF-α blockers, a variety of medical recommendations recommend pre-screening for important infections, including tuberculosis and hepatitis." (PMID 33519819, 2020). "IHC staining identified increased vimentin especially localized to granulomas in sarcoidosis patient spleens and stimulation of sarcoid peripheral blood mononuclear cells with vimentin induced higher IFN-γ and TNF-α secretion compared to those of tuberculosis patients or healthy controls." (PMID 33036432, 2020). "In addition, Rv2041c was related to high levels of TNF-α, IL-6 and IL-12p40 in bovine macrophages and induced an increase in the secretion of IFN-γ and TNF-α in lymphocytes, either in latent and active tuberculosis in mice models." (PMID 33291531, 2020). "Inhibition of this cytokine goes along with deterioration or reactivation of tuberculosis, absence of TNF-α is associated with fatal tuberculosis progression." (PMID 33057074, 2020). "Interferon-γ release assays rely on the fact that T-lymphocytes release this cytokine when exposed to tuberculosis-specific antigens and are useful in testing for latent tuberculosis infection before initiating biologic therapy, such as anti-tumor necrosis factor agents." (PMID 32459801, 2020). "The well-documented risk of tuberculosis progression associated with anti-TNF-α treatment highlighted the central role of TNF-α for the maintenance of protective immunity, although the rate of tuberculosis detected among patients varies with the nature of the drug." (PMID 32069329, 2020). "Especially, potentially Mtb infected individuals with high risk of tuberculosis disease progression (i.e., young children, HIV co-infected individuals, patients treated with anti-TNFα immune modulatory drugs) may benefit from this test." (PMID 31333654, 2019). "There are four steps between TNF-α and anti-tuberculosis immunity: (i) Assist in the activation of macrophages; (ii) The formation and maintenance of tuberculous granuloma; (iii) The regulation of immune response; (iv) Regulation of osteoclast differentiation, activation and apoptosis." (PMID 31072917, 2019). "Long-term treatment with corticosteroids and sometimes anti-TNF drugs may be complicated by severe opportunistic infections such as fungal infection, tuberculosis, or CMV." (PMID 30707321, 2019). "However, side effects of TNF-α inhibition have been reported, particularly in the form of exacerbation of infections such as tuberculosis." (PMID 31620105, 2019). "In addition, no available data exist for the management of latent or active tuberculosis during PD-1/PD-L1 blockade; for this reason, therapeutic guidelines are adopted from the management of patients receiving TNF-a inhibition." (PMID 31484550, 2019). "TNF-α is a factor both in the protection against tuberculosis and in immunopathology." (PMID 30583589, 2018).
tuberculosis (continued). "Indeed, blocking GM-CSF triggered the overproduction of anti-inflammatory IL-10, while TNFα and IL-12, pro-inflammatory cytokines which play a key role for the host-response to tuberculosis, were reduced." (PMID 29872095, 2018). "Other studies have shown the importance of TNF-α in patients with tuberculosis." (PMID 30588415, 2018). "Characteristics of 2 patients who developed active tuberculosis during TNF inhibitor treatment." (PMID 29975703, 2018). "Here we evaluated the impact of TNF-α blockade by Infliximab on the ability of PBMCs derived from active and clinically cured tuberculosis patients and PPD+ healthy donors to form a granulomatous reaction through an in vitro model using mycobacterial antigens-coated polyacrylamide beads." (PMID 29543912, 2018). "In unstimulated samples, patients with HIV-tuberculosis had higher percentages of tumor necrosis factor (TNF)-α+ monocytes compared with controls and higher supernatant concentrations of colony-stimulating factor (CSF)-3 and IFN-ɣ, whereas supernatant concentrations of IL-1β and IL-8 were lower." (PMID 28369200, 2017). "However, TNF-α monoclonal antibodies could be associated with low incidence of severe adverse effects such as induction of malignant lymphomas, infections, congestive heart failure, a lupus-like syndrome, induction of auto-antibodies, injection site reactions, and high incidence of tuberculosis." (PMID 28770521, 2017). "To evaluate the risk of infection using anti-TNF-α strategies, we compared a vaccine directed against murine TNF-α we developed by coupling murine TNF-α to KLH (TNFKi) and etanercept, the anti-TNF-α treatment associated with the lowest occurrence of infections, namely iatrogenic tuberculosis." (PMID 29184553, 2017). "Both histoplasma and tuberculosis have been increasingly reported with the use of TNF-α inhibitor." (PMID 28086756, 2017). "In S. pneumoniae stimulations, percentages of IL-6+ and TNF-α+ monocyte counts (q = 0.003) and IL-6+ absolute monocyte (q = 0.003) counts were lower in HIV-tuberculosis patients, as were percentages and absolute counts of IL-6+ (q = 0.003) and TNF-α+ (q = 0.01) neutrophils." (PMID 28369200, 2017). "However, managing and preventing flares of AS following discontinuation of TNF inhibitor is as much of a challenge to the clinicians treating tuberculosis itself." (PMID 27101309, 2016). "However, there is currently insufficient information on patient outcomes following resumption of TNF inhibitor treatment during ongoing anti- tuberculosis treatment." (PMID 27101309, 2016). "TNF-α is a fundamental factor for fighting intracellular bacteria and is therefore not surprising that TNF-α inhibition was shown to increase the risk for reactivation of tuberculosis." (PMID 28083070, 2016). "Increased circulating TNFα (one of the main proinflammatory cytokines) with concomitant clinical deterioration after the initiation of therapy in HIV-negative (HIV−) patients with severe tuberculosis has also been reported." (PMID 27297079, 2016). "Co-infecting pathogens increase HIV viral replication through de-repression of the transcriptional promoter (active tuberculosis), activation by antigen presenting cells and increase in TNF-α secretion (malaria), and transcriptional activation and cytokine release (HSV-2)." (PMID 27649908, 2016). "We suggest that early resumption of TNF inhibitors in AS patients could be safe under effective coverage of tuberculosis." (PMID 27101309, 2016). "The belief that tuberculosis is aggravated by continued use of TNF inhibitor may have led to the almost universal recommendation to discontinue TNF inhibitor." (PMID 27101309, 2016). "Anti-TNF-α therapy was withheld in most of these cases because of the possibility of respiratory infection or severe symptoms of sarcoidosis, and in some cases systemic corticosteroid and/or anti tuberculosis therapy were tried." (PMID 26864464, 2016).
tuberculosis (continued). "Moreover, cases with clinical and radiological deterioration during appropriate anti-tuberculosis treatment, termed paradoxical response, have been reported after stopping TNF inhibitor and successfully treated with re-addition of TNF inhibitor." (PMID 27101309, 2016). "Indeed, clinicians were concerned by the increased prevalence of tuberculosis in patients receiving TNF inhibitors, and particularly by the noticeable emergence of extra-pulmonary/disseminated and rapidly progressive tuberculosis." (PMID 27101309, 2016). "The inconsistencies and conflicts between recommendations, along with the clinician’s necessity to control AS disease activity, have led many physicians in our registry to individually resume TNF inhibitors in AS patients who have been diagnosed as having active tuberculosis." (PMID 27101309, 2016). "That a recent human clinical trial found that consumption of milled vegetative parts of S. frutescens in capsules might promote tuberculosis, is consistent with what would be expected if host production of TNF-α and IL-1β was diminished." (PMID 27575007, 2016). "TNF-α is crucial in protection against other respiratory infections such as tuberculosis." (PMID 26837619, 2016). "Despite recommencement of TNF inhibitor during or after tuberculosis treatment, the tuberculosis were treated successfully in all patients as scheduled, and did not recur during follow-up [median 33.8 (IQR 20.8–66.7) months; early resumers 37.0 (20.8–67.4) and late resumers 33.6 (18.5–52.7)]." (PMID 27101309, 2016). "TNF- α contributes both to the protection against tuberculosis and to immunopathology." (PMID 26359865, 2015). "The role of anti-TNF-α therapy in cases of active tuberculosis is still subject to discussion." (PMID 26273486, 2015). "Recent publications suggest that the accuracy in discriminating LTBI from active tuberculosis can be improved by parallel assessment of the secreting profile of T-cells for other cytokines, such as interleukin (IL)-2 and/or tumor necrosis factor (TNF)-α." (PMID 25785445, 2015). "While microglia were reported to be the primary source of TNF during CNS infection, we and others have shown that different cell types have hierarchical importance as sources of TNF in determining the outcome of tuberculosis disease." (PMID 26112704, 2015). "Furthermore, there have been reports of paradoxical responses in patients who developed tuberculosis after discontinuation of anti-TNF-α agents." (PMID 24576098, 2014). "In our study, tuberculosis patients presented significantly higher TNF-α levels than did controls." (PMID 24558401, 2014). "The development of a more effective vaccine against M. tuberculosis in the near future is highly desirable not only for the prevention of early progression of primary tuberculosis but also for the decline of patients infected with disseminated tuberculosis induced by aging and/or TNF-α inhibitors." (PMID 25317081, 2014). "Similar to anakinra, canakinumab has not been associated with the risk of tuberculosis reactivation, indicating that blocking the IL-1 pathway is safer in comparison with blocking TNF-α." (PMID 24884602, 2014). "There is data to suggest that the risk of tuberculosis is not constant for all anti-TNFα medications, with soluble TNFα receptors resulting in a lower risk of infection than monoclonal antibodies." (PMID 25414636, 2014). "Our functional data therefore partially corroborates and extends earlier observations that measurement of the frequency of M. tuberculosis-specific CD4+ effector-like cells secreting IFN-γ and/or TNF-α can distinguish active tuberculosis from latent tuberculosis infection." (PMID 23966657, 2013). "The frequency of PPD-specific CD4+ TNF-α-only-secreting T cells with an effector phenotype accurately distinguished active tuberculosis from latent tuberculosis infection with an area under the curve of 0.99, substantially more discriminatory than measurement of function alone." (PMID 23966657, 2013).
tuberculosis (continued). "Studies have suggested that the presence of trifunctional cells secreting IFN-γ, IL-2, and TNF-α correlates with active tuberculosis, but our data did not support this association." (PMID 23966657, 2013). "Cytokines such as interleukin-1β (IL-1β), tumor necrosis factor- α (TNF-α) and transforming growth factor β (TGF-β) have been implicated in the development of fibrosis in the context of a chronic inflammatory disease such as tuberculosis." (PMID 24155965, 2013). "Previous data indicated that measurement of CD4+ M. tuberculosis-specific TNF-α-only secreting cells might serve as an accurate biomarker of active tuberculosis." (PMID 23966657, 2013). "Highly elevated levels of cytokines primarily produced by macrophages and dendritic cells (IL-6, MCP-1, TNF-α, IL-10) in M. tuberculosis-PbNK65 co-infected animals indicate that immune regulation is significantly impaired when malaria is concurrent with tuberculosis in mice." (PMID 23110184, 2012). "Neutralization of TNF-α in murine models results in tuberculosis aggravation or reactivation." (PMID 23251798, 2012). "TNF-α blocking has dramatic effects on the progression of tuberculosis in experimental models." (PMID 23251798, 2012). "Tumor necrosis factor alpha (TNF-α) plays a key role in the containment of tuberculosis." (PMID 23192010, 2012). "Moreover, considering feasibility and cost-effectiveness, it is hard to recommend the routine use of QTF test for screening latent tuberculosis before treatment with TNF-α antagonists in countries with a high prevalence of tuberculosis." (PMID 22709461, 2012). "During tuberculosis disease, the poor nutrient intake or poor appetite is probably determined by the inflammatory responses to tuberculosis (including release of tumor necrosis factor-alpha) and its interaction with the metabolic pathways that lead to anorexia." (PMID 23217171, 2012). "It is theorized that the partial rather than complete TNF blockade may allow for some preservation of the beneficial and anti-inflammatory functions of TNF-α in tuberculosis immunity thereby reducing the incidence of tuberculosis." (PMID 23304607, 2012). "The meta-analysis involving 2723 subjects did not detect any association between the TNF -238G/A polymorphism and tuberculosis susceptibility." (PMID 23192010, 2012). "Thus, the findings of these researchers support our data and suggest a possible TNF-α/NF-κB mechanism of cilostazol action in our tuberculosis model systems." (PMID 22319585, 2012). "While the increased susceptibility of HTLV-1 infected patients to acquire tuberculosis may be due to impaired TNF-α production, the severity of tuberculosis in HTLV-1 infected individuals may be related to an increased inflammatory response." (PMID 22925731, 2012). "While TNF has long been known as a key determinant in controlling tuberculosis, these results in the zebrafish embryo model provided direct evidence that TNF signaling is protective during the early stages of mycobacterial infection in the absence of adaptive immunity." (PMID 21366518, 2011). "We next asked whether granuloma structures were formed in the presence of Tm-TNF during tuberculosis reactivation." (PMID 22132068, 2011). "Interestingly, bacterial re-emergence is contained in Tm-TNF mice during the initial phases of tuberculosis reactivation, indicating that Tm-TNF sustains immune pressure as in WT mice." (PMID 22132068, 2011). "In summary, our findings suggest that the polymorphisms present in and around the TNF genes are unlikely to be the major risk factors for tuberculosis in Asian Indians." (PMID 20537163, 2010). "Tuberculosis in patients treated with anti-TNF agents may present with extrapulmonary or disseminated disease." (PMID 20606887, 2010). "Thus, clinicians should be vigilant in monitoring for tuberculosis in their patients treated with TNF-α inhibitors." (PMID 20606887, 2010).
tuberculosis (continued). "Our study also gains support from others which report a lack of association between TNF gene polymorphisms and tuberculosis in different populations." (PMID 20537163, 2010). "TNF-α plays an important role in granuloma formation in tuberculosis." (PMID 20537163, 2010). "However, recent reports of reactivation of TB (tuberculosis) after anti-TNF therapy raised question on their safety." (PMID 19742267, 2008). "Reactivation of tuberculosis may occur on treatment with anti-TNF-α agents, as TNF-α plays a key role in host defense against mycobacterial infection, particularly in granuloma formation and inhibition of mycobacterial dissemination." (PMID 20040934, 2008). "However, recent reports of serious infections like tuberculosis, demyelinating and neurodegenerative diseases, pancytopenia, cardiovascular diseases, etc. after anti-TNF therapy raised questions on their safety." (PMID 19742267, 2008). "For this reason, we have decided to investigate therole of leptin and TNF-α in tuberculosis." (PMID 17497033, 2007). "We subsequently investigated LPS-induced CCL2, CXCL8 and TNFα in tuberculosis patients." (PMID 16001981, 2005). "We report occupational transmission of extensively drug-resistant tuberculosis (TB) to a healthcare worker in France receiving tumor necrosis factor α inhibitor therapy." (PMID 41863610, 2026). "A skin reaction of 5 mm or greater is considered positive for close contact with cases of tuberculosis, persons with HIV infection, immunosuppressed individuals, persons with evidence of current or past TB, and those receiving TNF‐blocking agents." (PMID 40390769, 2025). "Notably, TNF levels tend to decline following anti-tuberculosis therapy, and geographic and population-based factors may contribute to inter-individual differences in cytokine profiles." (PMID 40427602, 2025). "The reactivation of latent tuberculosis (TB) can occur after initiating therapy with anti-TNF agents, often presenting with pulmonary manifestations, constitutional symptoms, and extra-pulmonary features." (PMID 39807347, 2025). "Anti-TNF therapy in adults with rheumatological diseases and IBD is associated with an increased risk of tuberculosis (TB) reactivation." (PMID 39861147, 2025). "Of note, adalimumab, a monoclonal antibody targeting tumour TNF-alpha (TNF-α), has been associated with an elevated risk of tuberculosis (TB) compared to other anti-TNF-α agents." (PMID 39493161, 2024). "This was characterized by significantly elevated pro-inflammatory cytokines such as G-CSF, TNF-α, IL-1α, IL-1β, and IL-6, excessive neutrophil infiltration, and reduced pulmonary lymphocyte levels as tuberculosis (TB) progressed." (PMID 39178329, 2024). "Thus, Mtb could overcome the host’s battle against tuberculosis by expressing specific mycobacterial proteins and reducing the synthesis of TNF-α." (PMID 39519352, 2024). "Three months after restarting anti-TNF, he presented with disseminated pansensitive M tuberculosis TB." (PMID 38957691, 2024). "In addition, the TET2 gene also affects the host’s resistance to tuberculosis, the specific mechanism being that the binding of Tet2 to NF-κB induces the demethylation of TNF, where NF-κB is an important factor affecting the phenotypes of cell proliferation, apoptosis and inflammation." (PMID 38200892, 2024). "Anti-TNF-α agents have the potential to trigger the reactivation or dissemination of Mycobacterium tuberculosis, leading to active TB." (PMID 38222988, 2024). "TNF inhibitors increased the risk of tuberculosis but not that of herpes zoster." (PMID 39070789, 2024). "Latent tuberculosis (TB) infection screening before inducing anti-tumor necrosis factor (anti-TNF) alpha agents is important to prevent TB reactivation." (PMID 37443475, 2023).